PRMT5 (protein arginine methyltransferase 5)
Diseases named in the same sentence as PRMT5 in open-access papers (continued):
Sharing a sentence is not in itself a finding about the gene and the disease.
medulloblastoma (continued). "To confirm whether endogenous PRMT5 physically interacts with MYC protein in medulloblastoma, we performed a co-immunoprecipitation experiment in MYC-driven HD-MB-03 medulloblastoma cells using MYC and PRMT5 antibodies." (PMID 31694585, 2019). "Our results reveal the regulation of MYC oncoprotein by PRMT5 and suggest that targeting PRMT5 could be a potential therapeutic strategy for MYC-driven medulloblastoma." (PMID 31694585, 2019). "Here, we showed that PRMT5 is a novel regulator of MYC protein in medulloblastoma." (PMID 31694585, 2019). "Given that neural stem or cancer stem cells have profound impact on driving medulloblastoma tumorigenesis and recurrence, there might be role of PRMT5 in regulating self-renewal capacity of medulloblastoma tumor initiating cells." (PMID 31694585, 2019). "The exact MYC oncogenic programs regulated by PRMT5 in medulloblastoma are largely unknown." (PMID 38136401, 2023). "A variety of PRMT5 enzymatic inhibitors are currently applied in clinical trials of myelodysplastic syndrome, acute myeloid leukaemia, breast cancer and B cell non-Hodgkin lymphoma, prompting for further investigation in medulloblastoma [NCT03614728, NCT03573310, NCT02783300]." (PMID 34195095, 2021). "However, the role of PRMT5 and its association with MYC in medulloblastoma are unexplored." (PMID 31694585, 2019). "EPZ015666 significantly downregulates the higher expression of PRMT5 and MYC in medulloblastoma cells, suggesting it has therapeutic potential for MYC-driven medulloblastoma." (PMID 38136401, 2023). "Treatment with PRMT5 inhibitor EPZ015666 resulted in decreased MYC protein levels and medulloblastoma cell growth, indicating that PRMT5 inhibitors are potential treatments for MYCN-driven cancer." (PMID 36770809, 2023). "Knockdown of PRMT5 in medulloblastoma cells suppresses cell growth by diminishing MYC stability, supporting the functional role of the PRMT5–MYC interaction complex in medulloblastoma." (PMID 38136401, 2023). "PRMT5 plays a key role in cell functions and processes in MYC-driven medulloblastoma by stabilizing the MYC protein." (PMID 38136401, 2023). "The colocalization of PRMT5 and MYC suggests that PRMT5 forms a complex with MYC and supports its stabilization in MYC-amplified medulloblastoma cells." (PMID 38136401, 2023). "PRMT5 expression correlates with MYC expression in both primary medulloblastoma and medulloblastoma cell lines." (PMID 33440687, 2021). "Further, we showed that knockdown of PRMT5 suppressed medulloblastoma cell growth by inhibiting MYC expression, suggesting a functional role of PRMT5-MYC interaction in medulloblastoma tumorigenesis." (PMID 31694585, 2019). "Results from this analysis showed that high expression of PRMT5 was strongly correlated (R-value = 0.531; p-value = 2.51e-05) with high MYC in Group 3 medulloblastoma." (PMID 31694585, 2019). "Our data on PRMT5 knockdown in MYC-amplified medulloblastoma cells showed that PRMT5 can regulate the stability of MYC protein by physically interacting with it, suggesting MYC regulation by PRMT5 at the post-translation level." (PMID 31694585, 2019). "We further examined the correlation between PRMT5 and MYC expression at the protein levels by western blotting in non-MYC (Daoy, ONS-76) and three MYC-driven (D-283, D-341, HD-MB-03) medulloblastoma cell lines compared to normal cerebellum." (PMID 31694585, 2019). "Here, we report the role of PRMT5 as a novel regulator of MYC and implicate PRMT5 as a potential therapeutic target in MYC-driven medulloblastoma." (PMID 31694585, 2019). "To further authenticate this correlation at the protein level, we examined the expression of PRMT5 and MYC by immunohistochemistry in Group 3 medulloblastoma tumor samples (n = 6) compared to normal pediatric cerebellum (n = 4)." (PMID 31694585, 2019).
medulloblastoma (continued). "We next analyzed the correlation between PRMT5 and MYC mRNA expression across medulloblastoma subgroups using Pfister (n = 223) cohort at the R2 genomic analysis platform." (PMID 31694585, 2019). "Together, these results suggest that PRMT5 physically interacts with and stabilizes MYC in medulloblastoma cells at the post-translation level." (PMID 31694585, 2019). "We not only observed intensely high expression of PRMT5 and MYC protein in Group 3 medulloblastoma but also, a positive correlation with their predominantly nuclear co-expression." (PMID 31694585, 2019). "In the context of therapeutics, we observed dose-dependent efficacy of PRMT5 inhibitor EPZ015666 in suppressing cell growth and inducing apoptosis in MYC-driven medulloblastoma cells." (PMID 31694585, 2019). "We found that the protein levels of PRMT5 and MYC were significantly (p = 0.004) higher with more than 75% staining in Group 3 medulloblastoma samples than normal pediatric cerebellum tissues." (PMID 31694585, 2019). "The observation of physical interaction between PRMT5 and MYC indicates a potential functional role of this novel protein complex in medulloblastoma." (PMID 31694585, 2019). "It is important to note that this treatment is specific for MYC-driven medulloblastoma but not non-MYC-amplified medulloblastoma, as PRMT5 physically interacts with and regulates MYC protein expression." (PMID 39826691, 2025). "Highly expressed PRMT5 stabilizes MYC and promotes its expression in medulloblastomas." (PMID 38136401, 2023). "This review explores the current knowledge of the effectiveness of PRMT5 inhibitors in preclinical and preliminary clinical settings, which may aid in understanding how to treat MYC-amplified medulloblastoma more effectively and safely." (PMID 38136401, 2023). "PRMT5 regulates oncogenes, including MYC, that are often deregulated in medulloblastomas." (PMID 38136401, 2023). "Interestingly, the PRMT5 inhibitor EPZ015666 significantly suppressed cell growth and induced apoptosis in MYC-driven medulloblastoma cells." (PMID 34195095, 2021). "MYC-driven primary medulloblastoma tumours have high expression of the arginine methyltransferase PRMT5 compared to non-MYC medulloblastoma tumours and adjacent normal tissues." (PMID 34195095, 2021). "PRMT5 and MYC expression are positively correlated in medulloblastoma cells." (PMID 31694585, 2019). "Since PRMT5 is known to act during the G1 cell cycle phase, we sought to investigate whether inhibiting PRMT5 by EPZ015666 reduced medulloblastoma cell growth by disrupting the cell cycle." (PMID 31694585, 2019). "Mechanistic studies revealed that PRMT5 could elevate MYC expression and stability, enhancing medulloblastoma tumorigenicity." (PMID 31694585, 2019). "To investigate the role of PRMT5 on MYC function, we determined the effect of short-interfering RNA (siRNA)-mediated knockdown of PRMT5 on MYC expression and cell survival in MYC-amplified medulloblastoma cell lines." (PMID 31694585, 2019). "Our results also indicated that MYC-amplified cells show greater sensitivity to EPZ015666 compared to non-MYC amplified medulloblastoma cells, further supporting the role of PRMT5 acting in MYC-dependent manner." (PMID 31694585, 2019). "Although results showed some degree of correlation (R-value = 0.069–0.284; p-value = 0.111–0.606) of these genes in the other three medulloblastoma subgroups, none of these medulloblastoma subgroups showed a significant correlation between PRMT5 and MYC expression." (PMID 31694585, 2019). "However, the role of PRMT5 and its association with MYC in medulloblastoma have not been explored." (PMID 31694585, 2019). "Nonetheless, the function of PRMT5 and its interaction with MYC in MYC-driven medulloblastoma have not been fully investigated." (PMID 38136401, 2023). "We observed overexpression of PRMT5 in MYC-driven primary medulloblastoma tumors and cell lines compared to non-MYC medulloblastoma tumors and adjacent normal tissues." (PMID 31694585, 2019).
ovarian carcinoma (10 papers, 2015 to 2025). A malignant neoplasm originating from the surface ovarian epithelium. "Aberrant expression of PRMT5 has been reported to be associated with various human cancers, including epithelial ovarian cancer." (PMID 36999124, 2023). "Together, our results demonstrated that the expression of PRMT5 was highly increased in ovarian cancer and was associated with the overall survival of patients, suggesting that PRMT5 is a promising therapeutic target in ovarian cancer." (PMID 36999124, 2023). "We next explored the possible underlying signaling mechanisms of PRMT5‐driven ovarian cancer cell growth." (PMID 36999124, 2023). "However, the exactly roles and underlying mechanisms of PRMT5 contributing to the progression of ovarian cancer mediated by reprogramming cell metabolism remain largely elusive." (PMID 36999124, 2023). "Furthermore, the high expression of PRMT5 is associated with poor prognosis in patients with ovarian cancer." (PMID 36999124, 2023). "PRMT5 has been identified as a cancer target for its overexpression in lung, gastric, bladder, blood, breast, lung, and ovarian cancers and is correlated with poorer patient prognoses." (PMID 38000655, 2024). "In CaOV3, an ovarian cancer line, PRMT5 inhibition decreased markers of both HR and NHEJ, despite an increase in H2AX." (PMID 37596538, 2023). "What is more, the PRMT5 expression was higher in Taxol‐resistant ovarian cancer cell lines (A2780‐Taxol, C13*, and OVCAR3‐Taxol) than that in their corresponding parental cell lines (A2780, OV2008, and OVCAR3)." (PMID 36999124, 2023). "In this study, we found that PRMT5 is upregulated in ovarian cancer and promotes ovarian cancer cell glycolysis flux, tumor growth, and Taxol response." (PMID 36999124, 2023). "We found that the protein level of PRMT5 in ovarian cancer cells was significantly higher than that in normal proliferative cells (IOSE‐80 cells), although the mRNA level was only slightly increased." (PMID 36999124, 2023). "Given the important in ovarian cancer progression mediated by glycolysis flux, we applied previously designed and synthesized PRMT5 inhibitors, which block glycolysis flux, tumor growth, and enhance antitumor effects of Taxol in ovarian cancer." (PMID 36999124, 2023). "In the present study, we found that targeting PRMT5 activity by using DW14761 significantly suppressed ovarian cancer growth by regulating glycolysis through methylating ENO1." (PMID 36999124, 2023). "To determine how PRMT5 impacts glycolysis pathway in ovarian cancer cells, we examined the effect of PRMT5 on metabolic enzymes involved in glycolysis pathway." (PMID 36999124, 2023). "To further identify the role of glycolysis pathway as the downstream effector of PRMT5 in promoting ovarian cancer development, we explored the effects of PRMT5 on glycolysis pathway." (PMID 36999124, 2023). "In this manuscript, PRMT5 is highly expressed in ovarian cancer cells, and the expression level is higher in paclitaxel‐resistant cells." (PMID 36999124, 2023). "Meanwhile, knockdown of endogenous PRMT5 also robustly enhanced the sensitivity of ovarian cancer cells to Taxol treatment." (PMID 36999124, 2023). "In this study, we revealed a crucial role of PRMT5 in promoting ovarian cancer by regulating glycolysis flux." (PMID 36999124, 2023). "Nevertheless, more research is needed to explore the role of PRMT5 in cell metabolism, tumor growth, and Taxol responses of ovarian cancer." (PMID 36999124, 2023). "Lastly, the elevated expression of PRMT5 predicted the lower survival probability in ovarian cancer." (PMID 36999124, 2023). "We found that the expression of PRMT5 was positive in 22 (56.4%) of the 39 ovarian cancer patients, and it was significantly higher in ovarian cancer than normal tissues." (PMID 36999124, 2023). "In this study, we identified PRMT5 as a driver for ovarian cancer in promoting ovarian cancer progression." (PMID 36999124, 2023).
ovarian carcinoma (continued). "PRMT5 promotes ovarian cancer growth and Taxol response through enhancing glycolysis pathway, which mediated by regulating the symmetric dimethylation of arginine (SDMA) modification of ENO1." (PMID 36999124, 2023). "Overall, the increased exposure time and environmental stress increased the sensitivity of breast and ovarian cancer cell lines to inhibition of PRMT5, PARP, and the combination." (PMID 37596538, 2023). "To explore the clinical relevance of our findings, we performed immunohistochemistry (IHC) staining to determine the PRMT5 protein levels in clinical sample tissues of ovarian cancer (Cohort 1: ovarian cancer tissues [T, n = 39], normal tissues [N, n = 22])." (PMID 36999124, 2023). "Next, we checked the expression of PRMT5 in various human ovarian cancer cells (A2780, OV2008, OVCAR3, SKOV3, and Hey‐T30 cells)." (PMID 36999124, 2023). "Taken together, these data suggested that the antitumor effects of Taxol in ovarian cancer were significantly enhanced by targeting PRMT5." (PMID 36999124, 2023). "Together these data demonstrated that PRMT5 plays an important role in promoting ovarian cancer growth." (PMID 36999124, 2023). "We also found that in ovarian cancer and non-small cell lung cancer, PRMT5 inhibition in combination with PARP inhibitors acted synergistically, with a stronger killing effect on tumor cells and even re-sensitizing resistant ovarian cancer cells to PARP inhibitors." (PMID 40240755, 2025). "In vitro, PRMT5 inhibition increased markers of DNA damage in breast and ovarian cancer cell lines, and combination with PARP inhibitor produced additive to synergistic growth inhibition in both cancer cell lines and 3D clonogenic patient derived xenograft (PDX) models." (PMID 37596538, 2023). "However, after analyzing 32 patients who provided prognostic information in this library, we found that patients with high PRMT5 expression predicted poor prognosis in ovarian cancer." (PMID 36999124, 2023). "Indeed, the knockdown of endogenous PRMT5 significantly enhanced the antitumor effects of Taxol on ovarian cancer." (PMID 36999124, 2023). "Meanwhile, PRMT5 promotes the proliferation of ovarian cancer." (PMID 36999124, 2023). "Interestingly, we also found that PRMT5 was highly expression in ovarian cancer tissues than normal ovarian tissues based on public databases and our data cohort." (PMID 36999124, 2023). "We found that the levels of PRMT5 were evidently increased in ovarian cancer." (PMID 36999124, 2023). "Thus, ovarian cancer cells were treated with different concentrations of DW14761 or DW14800 to evaluate the inhibitory effect of the two molecules on ovarian cancer by targeting PRMT5." (PMID 36999124, 2023). "We found that knockdown of PRMT5 with siRNA decreased lactate production in ovarian cancer cells." (PMID 36999124, 2023). "In this study, we explored whether targeting PRMT5 could increase the sensitivity of ovarian cancer to Taxol treatment." (PMID 36999124, 2023). "Notably, although the protein level of PRMT5 was significantly increased in ovarian cancer cells, the increase at the mRNA level was relatively weak." (PMID 36999124, 2023). "Here, we report that PRMT5 is highly expressed and correlates with poor survival in ovarian cancer." (PMID 36999124, 2023). "Thus, the following investigations were focused on the mechanism and role of PRMT5 in promoting ovarian cancer." (PMID 36999124, 2023). "To determine whether the anti-proliferative activity of niraparib could be enhanced by PRMT5 inhibition, we evaluated the anti-proliferative effects of the combination on homologous recombination proficient breast and ovarian cancer cell lines." (PMID 37596538, 2023). "Thus, we first reported that PRMT5 enhances glycolysis in ovarian cancer by interacting with and methylating ENO1." (PMID 36999124, 2023). "Lastly, we found that PRMT5 was also increased in various human ovarian cancer cells." (PMID 36999124, 2023).
ovarian carcinoma (continued). "This reminds us that posttranscriptional regulation may be an important mechanism for the high expression of PRMT5 in ovarian cancer and deserves further exploration." (PMID 36999124, 2023). "Furthermore, we found that PRMT5 was also highly expressed in ovarian cancer tissues based on four other GEO databases (GSE66957, GSE120259, GSE12470, and GSE38666)." (PMID 36999124, 2023). "Evidence has emerged that PRMT5 acts as an oncogene in ovarian cancer." (PMID 30064416, 2018). "Therefore, our results suggested that PRMT5 may be a potential therapeutic target in ovarian cancer." (PMID 36999124, 2023). "Furthermore, the finding addresses that PRMT5 could substantially promote growth and proliferation of ovarian carcinoma cells depending on E2F-1." (PMID 30064416, 2018). "The down-regulation of PRMT5 may be a potential therapeutic target in malignant ovarian tumors." (PMID 30064416, 2018). "The anti-proliferative activity of the combination of PRMT5 and PARP inhibitors was evaluated using in vitro models of breast and ovarian cancers using both cell lines and ex vivo patient derived xenografts." (PMID 37596538, 2023). "Moreover, we found that targeting PRMT5 could enhance antitumor effect of Taxol in ovarian cancer." (PMID 36999124, 2023). "PRMT5, PRMT1, DDAH1, DDAH2, NOS2, ARG1, and ARG2 were all found to be up-regulated in the stage I/II or stage III/IV ovarian cancer tissues compared to normal tissues." (PMID 37684587, 2023). "Together, our data reveal a novel role of PRMT5 in promoting ovarian cancer growth by controlling glycolysis flux mediated by methylating ENO1, and highlights that PRMT5 may represent a promising therapeutic target for treating ovarian cancer." (PMID 36999124, 2023). "In summary, our study suggested the mechanisms and roles of PRMT5 in promoting ovarian cancer growth, and targeting PMRT5 could be provided new potential clues for the treatment of ovarian cancer." (PMID 36999124, 2023). "First, we found that the expression levels of glycolytic enzymes were not changed in PRMT5 knockdown ovarian cancer cells compared with the control group." (PMID 36999124, 2023). "Protein arginine methyltransferase 5 (PRMT5) is a major type II enzyme responsible for symmetric dimethylation of arginine (SDMA), and plays predominantly roles in human cancers, including in ovarian cancer." (PMID 36999124, 2023). "While no clinical trial of a PRMT5 inhibitor for ovarian cancer has been initiated, several studies have demonstrated the inhibition of ovarian cancer cell growth and induction of apoptosis with PRMT5 inhibition or siRNA knockdown." (PMID 37684587, 2023). "Indeed, suppressing PRMT5 using shRNA or inhibitors (DW14761 and DW1480) significantly reduced ovarian cancer colony formation, cell proliferation, and tumor growth." (PMID 36999124, 2023). "It has been reported that PRMT5 is highly expressed in ovarian cancer, but no mRNA has been detected." (PMID 36999124, 2023). "In addition, targeting PRMT5 with shRNA reduced extracellular acidification rate (ECAR) in ovarian cancer cells." (PMID 36999124, 2023). "However, how inhibition of PRMT5 enhances antitumor response of Taxol in ovarian cancer was not explored in this study." (PMID 36999124, 2023). "In addition, we demonstrated that PRMT5 is a critical enzyme for ENO1 arginine symmetric dimethylation modification and enhance its activity, which regulates glycolysis pathway, and promotes ovarian cancer growth." (PMID 36999124, 2023). "However, the roles and mechanisms of PRMT5 in controlling ovarian cancer progression have not yet to be fully determined." (PMID 36999124, 2023). "However, the function of DW14761 by targeting PRMT5 in ovarian cancer has not been explored." (PMID 36999124, 2023).
ovarian carcinoma (continued). "Notably, gene clusters of PRMT1/PRMT5 and DDAH1/DDAH2/ARG2 persisted, while other gene tree relationships and expression significances differed between the two comparisons: normal tissue versus stage I/II ovarian cancer and stage I/II versus stage III/IV ovarian cancer." (PMID 37684587, 2023).